GTF2F2 (general transcription factor IIF subunit 2)
Description:
TFIIF is a general transcription initiation factor that binds to RNA polymerase II and helps to recruit it to the initiation complex in collaboration with TFIIB.
Synonyms: RAP30; TFIIF; BTF4; TF2F2
Tractability: Small molecule: a structure with a bound ligand is known; it has a binding pocket of medium quality. PROTAC: ubiquitination databases record sites on it; its protein half-life has been measured.
Gene: Protein-coding gene on chromosome 13 (45,120,443 to 45,284,907, forward strand). Ensembl gene ENSG00000188342.
Subcellular location: Nucleus
Subcellular location (Human Protein Atlas): Nucleoplasm; Microtubules
Pathways (Reactome):
Disease: Abortive elongation of HIV-1 transcript in the absence of Tat; Dengue Virus-Host Interactions; Formation of HIV elongation complex in the absence of HIV Tat; Formation of HIV-1 elongation complex containing HIV-1 Tat; Formation of the HIV-1 Early Elongation Complex; HIV Transcription Initiation; HIV elongation arrest and recovery; Pausing and recovery of HIV elongation; Pausing and recovery of Tat-mediated HIV elongation; RNA Pol II CTD phosphorylation and interaction with CE during HIV infection; RNA Polymerase II HIV Promoter Escape; Signaling by FGFR2 IIIa TM; Tat-mediated HIV elongation arrest and recovery; Tat-mediated elongation of the HIV-1 transcript; Transcription of the HIV genome; Viral Messenger RNA Synthesis
Gene expression (Transcription): Formation of RNA Pol II elongation complex; Formation of the Early Elongation Complex; RNA Pol II CTD phosphorylation and interaction with CE; RNA Polymerase II Pre-transcription Events; RNA Polymerase II Promoter Escape; RNA Polymerase II Transcription Elongation; RNA Polymerase II Transcription Initiation; RNA Polymerase II Transcription Initiation And Promoter Clearance; RNA Polymerase II Transcription Pre-Initiation And Promoter Opening; RNA polymerase II transcribes snRNA genes
Metabolism of RNA: Processing of Capped Intron-Containing Pre-mRNA; mRNA Capping; mRNA Polyadenylation; mRNA Splicing - Major Pathway; mRNA Splicing - Minor Pathway
Signal Transduction: Estrogen-dependent gene expression; FGFR2 alternative splicing
Gene Ontology:
Molecular function: protein binding; RNA polymerase II general transcription initiation factor activity
Biological process: positive regulation of transcription by RNA polymerase II; transcription by RNA polymerase II; transcription elongation by RNA polymerase II; transcription initiation at RNA polymerase II promoter
Cellular component: microtubule cytoskeleton; nucleoplasm; nucleus; transcription factor TFIIF complex
Genetic constraint (gnomAD): Loss-of-function variants: 2 observed, 0.98 expected, observed/expected ratio (o/e) 2.03. That is too few expected variants to judge how well the gene tolerates losing a copy. Missense variants: 20 observed, 14.8 expected, observed/expected ratio (o/e) 1.35, 90% interval 0.94 to 1.85. Synonymous variants: 13 observed, 5.96 expected, observed/expected ratio (o/e) 2.18.
Homologues: Orthologues: chimpanzee GTF2F2 (100% identical), macaque GTF2F2 (99% identical), dog GTF2F2 (98% identical), mouse Gtf2f2 (98% identical), guinea pig GTF2F2 (98% identical), rabbit GTF2F2 (98% identical), rat Gtf2f2 (85% identical), tropical clawed frog gtf2f2 (83% identical), pig GTF2F2 (82% identical), zebrafish gtf2f2a (80% identical), zebrafish gtf2f2b (74% identical), Drosophila melanogaster TfIIFbeta (52% identical), and 1 more.
Diseases named in the same sentence as GTF2F2 in open-access papers:
GTF2F2 is named in the same sentence as 5 diseases in open-access papers, as found by Europe PMC text mining. Sharing a sentence is not in itself a finding about the gene and the disease. The quoted sentences say what the papers report.
depression (1 paper, 2022). "GTF2F2 may serve as a promising diagnostic biomarker and treatment target of depression, and this study provides a novel perspective and valuable information to explore the molecular mechanism of depression." (PMID 35711908, 2022). "Furthermore, differential and correlation analyses revealed that 9 transcription factors, 12 immune genes, and 2 m6A genes were associated with GTF2F2 in depression samples." (PMID 35711908, 2022). "This revealed that GTF2F2 might act as a satisfactory indicator for abundant mRNA modifications that regulate transcript processing and translation in depression." (PMID 35711908, 2022). "Finally, GTF2F2 was identified as a core gene for depression using GEO profiles with small sample sizes and imbalanced clinical data." (PMID 35711908, 2022). "According to the differential analysis results, GTF2F2 was significantly upregulated in depression samples compared with that in the corresponding controls, and the depression samples were grouped into high and low GTF2F2 expression subgroups based on the median GTF2F2 expression levels." (PMID 35711908, 2022). "GTF2F2 may affect pathogenesis of depression through the circadian process." (PMID 35711908, 2022). "Using an integrated bioinformatical analysis, for the first time to our knowledge, GTF2F2 was identified as a hub gene that may be vital for the onset and development of depression, which may serve as a promising novel indicator for the pathogenesis of depression." (PMID 35711908, 2022). "Further studies are needed to explore the correlation of GTF2F2 with immune response pathways such as the JAK-STAT and PI3K-Akt pathways and with inflammatory factors, which may improve the treatment of patients with depression." (PMID 35711908, 2022).
lung carcinoma (1 paper, 2021). "In a word, the gene GTF2F2 has an important role in the induction and progression of lung cancer, at the same time, it is subject to a fragile independent regulation." (PMID 34754623, 2021).
cancer (2 papers, 2021). A tumor composed of atypical neoplastic, often pleomorphic cells that invade other tissues. "GTF2F2 has been associated with cancer, human immunodeficiency virus (HIV-1) replication, and DNA repair pathways." (PMID 34281203, 2021). "In a word, we found that the target gene GTF2F2, which was independently regulated by miR-708-5p, also existed as a key node in the PPI network, and it is in the pathway associated with cancer." (PMID 34754623, 2021).
metabolic disorders (1 paper, 2023). "As GTF2F2 gene encodes general transcription factor IIF (TFIIF) subunit 2, the interaction between TFIIF and RPB5-mediating protein is critical to suppress the activated transcription, which might be involved in the biological events of energy metabolism, metabolic disorders and fertility." (PMID 36857354, 2023).
tumor (1 paper, 2021). "Further pathway analysis indicated that GTF2F2 participates in protein expression by binding with polymerase II, and it can regulate transcription and accelerate tumor growth." (PMID 34754623, 2021). "We found the important hub gene GTF2F2, which was independently regulated by miR-708-5p, and it interacted with RNA Pol II as a basal transcription factor to perform transcriptional functions and accelerate tumor growth." (PMID 34754623, 2021). "GTF2F2 binds with RNA polymerase II, and then participates in protein expression, which could regulate transcription and accelerate tumor growth." (PMID 34754623, 2021).